TSC2 (TSC complex subunit 2)
Diseases named in the same sentence as TSC2 in open-access papers (continued):
Sharing a sentence is not in itself a finding about the gene and the disease.
tumor (continued). "An inactivating mutation of the tumor suppressor genes, TSC1 or TSC2, leads to the mammalian target of rapamycin complex 1 (mTORC1) activation causing increased cell growth, making rapamycin and its analogs (like sirolimus) valuable treatment options for LAM." (PMID 39156285, 2024). "Specifically, in a genetic model of papillary renal cancer triggered by Tsc2 heterozygous inactivation, Pml genetic deletion accelerated tumor progression, and this was accompanied by increased mTOR activity in the kidney." (PMID 38730056, 2024). "Recent research showed that esteriol promotes circulatory tumor cells and pulmonary transplants of tuberculosis-deficient cells by increasing MMP2 production and activity of TSC2 faulty cells." (PMID 38877584, 2024). "Like other tumor suppressors, there are multiple classes of pathogenic mutations found in both TSC1 and TSC2 that contribute to disease." (PMID 39352796, 2024). "Injection of Tsc2-null tumor cells into the tail vein results in the growth of multiple lesions in the lungs, characterized by the expression of vascular endothelial growth factor D and the promotion of lymphangiogenesis." (PMID 39456169, 2024). "We also observed enrichment of sgRNAs targeting CDKN1B, PTEN, TSC1 and TSC2 in both cell types, suggesting deletion of these tumor suppressors provides a survival advantage." (PMID 38480701, 2024). "TSC2 is part of the tumour suppressor TSC complex that maintains mTORC1 inactive through the regulation of Ras homologue enriched in brain (Rheb)." (PMID 38431691, 2024). "The identified splice variant genes (CENPK, PKN1, KIAA1324, EMD, and TSC2) associated with response were mainly related to mitosis, PI3K–Akt cell survival/proliferation signaling, and tumor progression and metastasis." (PMID 39404386, 2024). "Deletion of Rictor/Tsc2 also resulted in an increased tumor burden, as shown in liver weight compared with the control group." (PMID 39325536, 2024). "In contrast, the results of a xenograft assay with ERO1α-overexpressing Tsc2 + / + MEFs showed that overexpression of ERO1α promotes tumor cell proliferation and angiogenesis in vivo." (PMID 38610018, 2024). "Inactivating mutations in the tumor-suppressor genes TSC1, TSC2, and STK11 are described as targets of TOR inhibitors in hamartoma syndromes and in urothelial carcinoma." (PMID 36855200, 2023). "Similar results were seen in Tsc2-deficient TTJ cells, with B7-H3 inhibition suppressing tumor growth by >50% and approximately doubling tumor-free survival." (PMID 36869048, 2023). "Based on the tumor growth curve, the increase in tumor volume in the TSC2-NC group was significantly different in the control and lapatinib groups (F = 8.187, P = 0.0005; one-way ANOVA)." (PMID 37160904, 2023). "Of these, 21 proteins were enriched in TSC2‐ EVs, with IL‐6, MMPs, VEGF, Galectin‐3 previously associated with mTORC1‐driven tumours." (PMID 37337371, 2023). "In xenograft tumour models, knockdown of Glrx in TSC2‐deficient LAM cells inhibited tumour growth and increased tumour cell apoptosis." (PMID 37478294, 2023). "The tumor suppressor genes TSC1 on chromosome 9q34 and TSC2 on chromosome 16p13 encode the tuberin and hamartin, respectively." (PMID 36915840, 2023). "It is worthwhile to note that, some tumor suppressors including LKB, TSC1, and TSC2 also exhibit tumor cell promotion function especially in some metabolic stresses conditions." (PMID 37543638, 2023). "The Tuberous Sclerosis Complex proteins TSC1 (hamartin) and TSC2 (tuberin) are key negative regulators of mTORC1 and play a critical role in tumor suppression." (PMID 36869048, 2023).
tumor (continued). "This further evidence of mTORC1‐independent links between TSC2 loss and VEGF expression has potential implications for the effectiveness of rapamycin treatment, especially for highly angiogenic tumours." (PMID 37337371, 2023). "JAK2 plays a major role in growth factor signaling and histone modifications, while TSC2 is a tumor suppressor that inhibits cell growth by downregulating the mTORC1 pathway." (PMID 38137511, 2023). "In summary, the present study identified increased expression of key enzymes in the sphingolipid biosynthesis pathway in LAM and AML tumor cells as well as in TSC2-null cells." (PMID 36927688, 2023). "Our studies show that suppression of ASAH1 using 17a and ASAH1 shRNA attenuates xenograft tumor progression and growth of renal cystadenomas in Tsc2+/– A/J mice." (PMID 36927688, 2023). "We next assessed the possible benefit of the ASAH1 inhibitor 17a in a xenograft tumor model in which Tsc2-null ELT3 luciferase-expressing cells were implanted subcutaneously into immunodeficient NOD/SCID-γ–null (NSG) mice." (PMID 36927688, 2023). "In prostate cancer, adiponectin inhibits tumor cell growth by suppressing VEGF-A-mediated tumor neovascularization via AMPK/tuberous sclerosis complex 2 (TSC2), resulting in inhibition of mTOR-mediated VEGF-A activation and decreased VEGF-A production." (PMID 37686525, 2023). "The in vivo targeting effect of rapamycin can eliminate TSC2-null xenograft tumor model growth, induce apoptosis, increase the survival rate of tumor-bearing mice, and prevent tumor regeneration after treatment." (PMID 37160904, 2023). "We also observed enrichment of sgRNAs against CDKN1B, PTEN, TSC1 and TSC2 in both cell types, suggesting deletion of these tumor suppressors provides a survival advantage." (PMID 37502925, 2023). "All 3 BLCA PDX models with TSC1/TSC2 deficiency were sensitive to RMC-5552, which caused significant tumor volume reduction in 2 of 3 PDX models, and delayed tumor growth in the third." (PMID 37909334, 2023). "The fundamental discovery of the Rheb-GAP tumor suppressor function of TSC2 positioned mTORC1 as a new drug target for the treatment of TSC." (PMID 36551683, 2022). "Rapamycin significantly decreased tumor growth in both WT and TSC2 KO xenografts consistent with decreased TFEB nuclear localization." (PMID 36357396, 2022). "Because the TSC1/TSC2 complex is the principal suppressor of mTORC1 signaling and hyperactivated mTORC1 is the main reason for tumor formation in TSC disease, Tsc1 − / − or Tsc2 − / − MEFs and TSC samples are excellent models for the study of mTORC1 signaling." (PMID 36217202, 2022). "We then examined tumor xenograft growth in WT and TSC2 KO cells in response to treatment with rapamycin and torin." (PMID 36357396, 2022). "Mutation in one of the two tumor suppressor genes, TSC1 encoding hamartin, and TSC2 encoding tuberin is accountable for approximately 85% of cases of this multisystemic tumor syndrome called TSC." (PMID 35600170, 2022). "Tuberous sclerosis complex (TSC) is an autosomal dominant genetic disorder caused by a mutation in either one of the two tumor suppressor genes: TSC1 at 9q34, encoding for hamartin, or TSC2 at 16p13.3, encoding for tuberin." (PMID 35743464, 2022). "Treatment of animal models of LAM with anti-PD-1 antibodies resulted in suppression of TSC2-null tumor growth and induction of tumor rejection." (PMID 35300340, 2022). "The tuberous sclerosis complex (TSC) is a multisystem disease genetically characterized by a loss of function in either of the two tumor suppressors, TSC1 (hamartin) or TSC2 (tuberin)." (PMID 35359406, 2022). "Knockout of TSC2 promoted the proliferation, migration, invasion, angiogenesis, and tumor growth abilities of TU177 cells, while these properties were significantly attenuated after depletion of ITGA5." (PMID 36438491, 2022). "Mutations in one of the tumor suppressor genes, TSC1 or TSC2, lead to an aberrant hyperactivation of the mammalian TOR pathway." (PMID 35639710, 2022).
tumor (continued). "The whole-exon sequencing (WES) results of the tumour sample showed missense single-nucleotide variations (SNVs) in TSC2 (NM_000548: exon 4:c.T311C:p." (PMID 36510186, 2022). "Another work identified increased expression of oncogenic pathways and mutations in known tumor suppressor genes such as VHL and TSC2 in tumor cells displaying HPD after therapy with anti-PD-1 therapy." (PMID 35922755, 2022). "For Tsc2-KO tumors, anti–PD-1 antibody administration remarkably decreased tumor growth compared with vehicle (P < 0.05)." (PMID 35119931, 2022). "TSC2 in complex with TSC1 has tumor suppressor functions via regulation of the mechanistic target of rapamycin kinase (mTOR) signaling pathway." (PMID 35962345, 2022). "The IHC results of tumor tissue indicated that pEGFR and pS6 were highly expressed in TSC2-depleted tumor tissue, and CD24 exhibited considerable positive expression." (PMID 36231025, 2022). "Then, we investigated the mechanisms of increased tumor-infiltrating CD8+ T cells in TSC1/TSC2-mutant tumors." (PMID 35119931, 2022). "The phosphorylation curve shows that the mTOR pathway is activated by the disrupted function of the TSC1/2 complex, which proves that the carcinogenic lineage of PEComa is a unique TSC2-related tumor." (PMID 35928867, 2022). "In order to further characterize potential functional redundancy of TFEB and TFE3 in the TSC2 KO background, we performed RNA-seq on tumor xenografts grown from WT, TSC2 KO, and TFEB KO, TFE3 KO and double TFEB/TFE3 KO cells." (PMID 36357396, 2022). "Taken together, our study provides a connection between mTOR-dependent tumor growth and CHK1/2, highlighting the importance of CHK1/2 inhibition as a potential antitumor strategy in TSC2-deficient tumors." (PMID 35359406, 2022). "We next assessed the in vitro tumor growth of Tsc2−/− MEFs when grown in soft agar in the presence or absence of APX3330." (PMID 36551683, 2022). "Next, the transwell assay found that TY52156 markedly weakened the capacities of migration and invasion of TSC2-deficient cells, indicating that inhibition of S1PR3 reduced the metastatic capacity of tumor cells." (PMID 36543771, 2022). "In our case, genetic alteration in the TSC2 gene was identified in tumor cells, so an mTOR inhibitor was started after the second relapse." (PMID 34542724, 2021). "Based on these findings of growth inhibition by ganetespib in vitro, we performed tumor xenograft experiments using the TSC2 null SNU-398 cell line." (PMID 33891611, 2021). "It has been reported that miR-21-3p promoted cell proliferation, migration and invasion through regulating TSC2/mTOR pathway, and augmented tumor proliferation via PI3K/AKT pathway." (PMID 34388112, 2021). "Tuberin (TSC2), a tumour suppressor, regulates the activity of mTOR that regulates protein synthesis, cell growth, and autophagy." (PMID 34395438, 2021). "Six have been indirectly linked to tumour malignancy and are thus new splicing targets to study (CAST, CSF1, PLOD2, SLK, SPAG9, TSC2)." (PMID 33845831, 2021). "TSC-LAM is caused by mutations in two tumour suppressor genes: TSC1 and TSC2, with consequent loss of function of hamartin and tuberin proteins, respectively." (PMID 33986388, 2021). "Tuberous sclerosis complex 1 (TSC1) is a tumor suppressor that combines with tuberous sclerosis complex 2 (TSC2) to block the catalytic Rheb–GTPase-activating protein (GAP) activity of TSC2." (PMID 33467535, 2021). "The TSC1-TSC2 complex, a tumor suppressor, forms when TSC1 and TSC2 bind via their coiled-coil domains to form an intracellular complex, which helps switch the protein Ras homolog enriched in brain (Rheb) from its active state, Rheb-GTP, to its inactive state." (PMID 34445268, 2021). "In cells, mTORC1 is negatively regulated by a heterodimer complex consisting of TSC1 and TSC2, which are the products of the tumor suppressor genes Tsc1 and Tsc2." (PMID 34199299, 2021).
tumor (continued). "In mice challenged with Tsc2–/– tumor cells, CAR T cells substantially and durably reduced the tumor burden, correlating with increased T cell infiltration." (PMID 34806651, 2021). "Next generation sequencing (NGS) confirmed the tumor was microsatellite stability (MSS), and a total of 6 gene mutations, TSC2, CREBBP, HIST1H3I, MAP2K4, SMAD4, and STK11 were detected." (PMID 34880877, 2021). "TSC2 is a tumor suppressor gene; it negatively regulates the cellular signaling networks that control cellular growth and proliferation." (PMID 34880877, 2021). "To further validate the correlation of LRP1B and TSC2 in HNSCC, we analyzed them in 1478 HNSCC samples and found that LRP1B was associated with tumor HPV status in HNSCC (P = 0.044)." (PMID 33994859, 2021). "The overactivation of PI3k/Akt/mTOR pathway promotes glycolysis and glucose-dependence, leading TSC1/TSC2 mutant tumor cells entering apoptosis after glucose withdraw." (PMID 33821877, 2021). "In vivo and in vitro studies found decreased TSC2 null cell survival and reduction in tumor size by chloroquine." (PMID 33119872, 2021). "We and another group previously reported that mTORC1 activation is sufficient for the spontaneous development of HCC in a mouse model in which the tumor suppressors tuberous sclerosis complex (TSC) 1 or TSC2 are lost." (PMID 34796113, 2021). "A tumor-agnostic registrational trial in cancers with TSC1 or TSC2 inactivating alterations is expected." (PMID 34442003, 2021). "The second subpopulation with IRS1 downregulation showed a significant increase in relative inhibitory phosphorylation of IRS1 and TSC2 anti-tumor protein and an increased activation of the mitogenic pathway associated with ERK1/2." (PMID 34684639, 2021). "A pathological examination revealed that both lesions were PEComa, and genetic alteration of the TSC2 gene was identified in tumor cells." (PMID 34542724, 2021). "TSC2 forms a heterodimer with TSC1 to act as a tumor suppressor, and TSC2 activates Rheb, a GTP-binding protein." (PMID 32708855, 2020). "In this study, the effects of ZA on TSC2-null cell proliferation and on the tumor progression and recurrence in LAM mouse models, were investigated." (PMID 32063747, 2020). "The effects to preventing TSC2-null tumor growth and inhibiting destruction of the lung tissue were enhanced when simvastatin was in combination with rapamycin." (PMID 33072782, 2020). "As a result, a mouse model with tumor-specific deletion of miR-10b in tumors arising spontaneously in mice would be a good tool to stablish the in vivo role of the miR10b/DAZAP1/TSC2 axis in ESCC in the future." (PMID 32308763, 2020). "Tuberous sclerosis complex (TSC) caused as a result of mutations in any of the two tumor suppressor genes, TSC1 and TSC2, leads to formation of localized tumor masses in multiple organs." (PMID 32742252, 2020). "Of genes previously reported as commonly mutated in PNETs, only PDGFRA and MTOR were found to be mutated in a few tumor samples, and other genes, including ATM, ATRX, TSC2, DAXX, VHL, and MEN1, were mutated only in individual samples." (PMID 32586046, 2020). "The TSC-1 and TSC-2 proteins form a complex and function as tumor suppressors by inhibiting mTORC1 kinase." (PMID 32397669, 2020). "Tuberosclerosis gene TSC1 (9q34) and TSC2 (16p13.3) are regulated by neurofibromin through mTOR activation, linking the three proteins in terms of their potential roles in tumour progression." (PMID 31443481, 2019). "UL38’s metabolic reprogramming role is dependent on its interaction with TSC2, a tumor suppressor that inhibits mTOR signaling." (PMID 30677091, 2019).
tumor (continued). "Loss of function mutations of the tumour suppressor TSC1 are seen in bladder cancer, while 25 different TSC2 mutation sites, mainly in or near the RAP-GAP domain, have been reported in pancreatic neuroendocrine tumours (PNET)." (PMID 35582282, 2019). "SGKs are homologous to Akt and these kinases display overlapping specificity and phosphorylate several substrates at the same residues, such as TSC2 to promote tumor growth by switching on the mTORC1 pathway." (PMID 31665227, 2019). "Copy number analysis from exome data indicated a possible deletion of TSC2 in a subpopulation of tumor cells." (PMID 31077186, 2019). "TSC2 is a tumor suppressor and well-known inhibitor of mTORC1, which globally regulates cellular metabolism in many contexts, e.g., fluctuations in nutrient availability or in response to various signal transduction pathways." (PMID 30677091, 2019). "In the second, AMPK activates the tumour suppressor complex that comprises the tuberous sclerosis proteins, Tsc1 and Tsc2 (Tsc1 and Tsc2 function together as a complex are hereafter denoted Tsc1/2)." (PMID 30814334, 2019). "Despite showing promise, rapalog monotherapy has been proven mostly insufficient in causing tumor regression, with notable exceptions of tumors showing mutations in mTOR itself, LOF mutations in TSC1 or TSC2." (PMID 30764584, 2019). "The rare PNET have also been found to have mTOR hyperactivity, with one study demonstrating that 85% of primary tumours had altered protein levels of the tumour suppressors TSC2 and PTEN." (PMID 35582282, 2019). "While AMPK is generally viewed as a tumor suppressor partly by phosphorylating TSC2 and Raptor, leading to inhibiting mTOR signaling, it can also display tumor-promoting activity by regulating NADPH and ROS levels in breast cancer." (PMID 30413706, 2018). "Immunohistochemistry revealed decreased TSC2 protein content and increased phospho-S6 in the tumor cells, demonstrating mTOR pathway activation." (PMID 29764404, 2018). "Genes that negatively interact with both TSC1 and TSC2 represent potential therapeutic targets (i.e. drugs inhibiting a negative interactor would be predicted to suppress the growth of tumor cells while leaving phenotypically normal cells unaffected)." (PMID 29343513, 2018). "To determine the effect of the anti-sense Nox4 in vivo, we subcutaneously inoculated LEF2 (Tsc2−/−) cells to generate tumor xenografts in nude mice." (PMID 29491408, 2018). "Targeted next generation sequencing (NGS) of MTOR, TSC1 and TSC2 genes in the primary tumor, metastasis and blood of the patient, revealed one inactivating TSC2 mutation (c.2739dup; p.K914*) in the tumor cells." (PMID 29764404, 2018). "Our data tested the synergistic effect of the combination of rapamycin+AICAR for treatment of kidney tumorigenesis in AML human and in TSC2+/− and TSC−/− fresh tubular cells isolated from normal and tumor kidney of TSC2+/− mouse and in TSC2+/− mouse model." (PMID 30250638, 2018). "Together, the WEE1 inhibitor can be used for TSC2-null tumor treatment by accelerating release from the G2/M DNA damage checkpoint dampened by hyperactivation of mTORC1." (PMID 30266942, 2018). "We observed that the combination of nelfinavir and mefloquine had a long-lasting effect on Tsc2−/− tumor spheroids, when compared to single drug treatments." (PMID 30308940, 2018). "Targeted NGS of MTOR, TSC1 and TSC2 genes was performed on DNA extracted from formalin-fixed paraffin-embedded primary tumor and hepatic metastasis, and the patient’s peripheral blood (TruSeq Custom Amplicon Low Input; Illumina)." (PMID 29764404, 2018). "Loss of TSC1, TSC2, or PTEN leads to hyperactivation of mTOR and therefore the cells and tissues deficient of these tumor suppressors are widely used in the study of mTOR signaling." (PMID 29362480, 2018). "These tumors are characteristically driven by deleterious mutations in the tumor suppressors TSC1 and TSC2, whose gene products typically act to inhibit mTOR." (PMID 30285856, 2018).